MMP9 (matrix metallopeptidase 9)
Diseases named in the same sentence as MMP9 in open-access papers (continued):
Sharing a sentence is not in itself a finding about the gene and the disease.
tumor (continued). "Among MMPs, the principal player is MMP-9 secreted by monocytes and OCs with MMP-13 derived from tumour cells acting as modulator in some specific steps of the differentiation process." (PMID 22032644, 2011). "The MMP-9 - VEGF loop not only supports angiogenesis and invasion but "forces hyperactive haematopoiesis" which aids tumour progression." (PMID 22005011, 2011). "In particular, MMP-2 and MMP-9, which can degrade ECM and activate many growth factors, play an important role in tumor invasion and metastasis." (PMID 22219636, 2011). "In this study, we also demonstrated that there was an inhibition NF-κB activity (JSH-23) in A431 tumor cells, which led to a suppression of the TG2-induced increases in Snail, MMP-9, and cell motility." (PMID 21777419, 2011). "Members of the MMP family of proteins promote tumor angiogenesis as well as cellular detachment, invasion, and metastasis, and some MMP family members, including MMP-2 and MMP-9, are reported to be regulated by IL-8 expression." (PMID 22235381, 2011). "Inhibition of PI3K activity (LY294002) in A431 tumor cells attenuated the TG2-induced activation of Akt and GSK-3β, and suppressed the increases in Snail, MMP-9, and cell motility." (PMID 21777419, 2011). "Transgelin (SM22α) is a cytoplasmic actin-binding protein, expressed by mesenchymal cells and tumor fibroblasts and which represses TGF-β-induced MMP-9 expression, reduces cell migration, and has tumor suppressor properties." (PMID 21549007, 2011). "For each tumor sample, the active and inactive forms of MMP2 and MMP-9 were measured by their gelatinolytic activities." (PMID 21726449, 2011). "The highly positive correlations of MMP-9 expression ratio with multiple location dissemination, higher UICC stages and larger tumor size were observed." (PMID 21548969, 2011). "Compared with groups II and III, the percentage of positive MMP-9, VEGF and PCNA tumor cells in group I was even higher (P < 0.05)." (PMID 20667141, 2010). "The MMPs (particularly MMP-2 and MMP-9) and VEGF expression has been studied also in three nasopharyngeal carcinoma human cell lines as factors that can contribute to tumor development and aggressiveness under stimulation of catecholamines." (PMID 20585601, 2010). "Accordingly, MMP-9, CD31 and factor-VIII expression were increased in the tumour sections in these mice compared with the tumour sections of mice with Daoy-SP2 cells." (PMID 20087345, 2010). "The MMP-9 induction reversed SPARC-mediated tumour growth inhibition by 50%, with a mean tumour volume of 30% of the empty vector control." (PMID 20087345, 2010). "In the present study, it was shown that expression of PCNA, MMP-9, VEGF, HGF and IL-6 in tumor tissues in groups I, II and III, which received incomplete RFA, increased remarkably." (PMID 20667141, 2010). "Since MMP-2 and MMP-9 play critical role in tumor cell invasion, we examined the effects of CD147 silencing on the enzyme activities of MMP-2 and MMP-9 using gelatin zymography." (PMID 20525232, 2010). "Dz13 upregulated the matrix metalloproteinase (MMP)-2 and MMP-9, and decreased expression of MT1-MMP (MMP-14) in cultured tumour cells." (PMID 20334687, 2010). "MDSCs also secrete large amounts of MMP-9, which regulates the bioavailability of VEGF in the tumor microenvironment, thus MDSCs increase VEGF bioavailability and indirectly increase tumor angiogenesis." (PMID 24281102, 2010). "In this study, we were able to determine the amount of mRNA of MMP-9 and TIMP-1 in the few residual tumour tissues that were available (n=3 for each group, i.e., RGZ-treated (4 weeks) or control mice)." (PMID 20068562, 2010). "Another derivate, galloyl glucose, blocked HT-1080 tumour invasion through gelatin by inhibiting matrix metalloprotease-2 (MMP-2) and MMP-9." (PMID 20424615, 2010). "This suggests that factors other than MMP-9 and VEGF are involved in SPARC-mediated inhibition of tumour growth." (PMID 20087345, 2010).
tumor (continued). "Expression of PCNA, MMP-9, VEGF, HGF and IL-6 in tumor tissues increased significantly in the RFA-treated groups compared with the control group, and of the increases were greatest in the 55°C group (P < 0.05)." (PMID 20667141, 2010). "TSP-1 is involved in both tumor cell adhesion and tumor cell invasion through multiple mechanisms including several adhesive domains within TSP-1 itself and upregulation of enzymes such as matrix metalloproteinase 9 (MMP-9)." (PMID 20631908, 2010). "Tumor derived MCP-1 and CCL5 induce macrophages to secrete angiogenic factors, such as IL-8, VEGF, MMP-9, FGF-2, tumor necrosis factor alfa (TNF-α) and PDGF." (PMID 24281035, 2010). "In summary, proteolytic enzymes MMP9, MMP2 and macrophages in stroma contribute to GC progression by facilitating tumor angiogenesis." (PMID 20950454, 2010). "It is this event that represents an important stage of tumor progression and is demonstrated principally by a coexpression of MMP-2 and MMP-9 in invasive and in situ melanoma." (PMID 20585601, 2010). "The percentage of positive MMP-9, VEGF and PCNA tumor cells in the RFA treatment groups were markedly higher than that in the control group (P < 0.05)." (PMID 20667141, 2010). "Since MMP-2 and MMP-9 play a critical role in tumor cell invasiveness, we examined the effect of risedronate on the enzyme activities of MMP-2 and MMP-9." (PMID 19624845, 2009). "It has thus been suggested that MMP-9 and NGAL are mainly secreted in blood by neutrophils infiltrating the tumor, and are separately excreted in urine where they subsequently form complexes." (PMID 19889214, 2009). "Pro-metastatic genes (VEGF-A, MMP-9 and CXCR4) are up-regulated, and the tumor inhibitory gene (RECK) is down-regulated in xenograft tumors developing in presence of PICP." (PMID 19226458, 2009). "The constitutive p38 MAPK pathway activation results in up-regulation of matrix metalloproteinase-9 (MMP-9), a critical factor in tumour angiogenesis and tumour homing." (PMID 19779621, 2009). "The results indicated that the ratios between MMP-2/RECK, MMP-9/RECK and MMP-14/RECK were significantly higher in the tumor than in adjacent non-tumor tissue samples (p = 0.0024, p = 0.0001 and p < 0.0001, respectively)." (PMID 19144199, 2009). "Among MMPs, MMP-2 (gelatinase A) and MMP-9 (gelatinase B), are present in large quantities in cancer tissues, and accumulating evidence indicates that MMP-2 and MMP-9 play critical role during tumor invasion and metastasis." (PMID 19624845, 2009). "Our results revealed that after separation, the metastasis potential of NPC-BM29 was confirmed by increased expression of 92-kDa type IV collagenases/gelatinase B (MMP-2 and MMP-9); both enzymes are involved in tumor cell invasion and metastasis." (PMID 19930697, 2009). "The positive cell number of CXCL12, CXCR4, MMP-2, MMP-9 and NGF expression of tumor cells in CXCL12-treated group was the highest." (PMID 18983683, 2008). "In experimental studies of cultured tumor cells infected with EBV that express LMP-1, overexpression of MMP-9 is observed, which is activated through the nuclear factor NFkB pathway." (PMID 18954439, 2008). "In addition, its has been recently shown that ATP causes shedding of metalloproteases (MMP9) and expression of indoleamine oxygenase; both activities may be very relevant for tumour progression as MMP9 release facilitates tumour invasion while indoleamine oxygenase has immunosuppressive activity." (PMID 18612415, 2008). "The positive positions of tumor cells for VEGF, NF-κB, MMP-2 and MMP-9 staining were located in the cytoplasm and for PCNA in the nucleus." (PMID 18983651, 2008). "MMP-2 and MMP-9 are members of MMPs family and they can functionally degrade collagen IV in ECM, a step essential for tumor invasion and metastasis." (PMID 18983651, 2008).
tumor (continued). "These CD34+ iMCs promote tumour growth by expression of the matrix metalloproteinases, MMP9 and MMP2, and the CC-chemokine receptor 1 (CCR1), and migrate towards the CCR1 ligand CCL9, highly increased in the tumour epithelium." (PMID 18506144, 2008). "A role for αVβ6-mediated production in the regulation of MMP-9 and MMP-3 have been reported in several tumor types and in untransformed keratinocytes." (PMID 19787098, 2008). "We can see clearly from the previous results that tumor-mesothelial cells adhesion up-regulate MMP-2 and MMP-9 expression." (PMID 19662219, 2007). "Disruption of CD44/MMP-9 cluster formation, by over expression of soluble or truncated cell surface CD44 reduces tumor invasiveness in vivo." (PMID 17343740, 2007). "Platelets physiologically contain MMP-9 and TIMP-1, and the use of serum has therefore been questioned in tumor marker studies." (PMID 19662197, 2007). "Fibroblast invasion-promoting capacity (IPC) was analyzed in relation to donor type (tumor or non-tumor patient), MMP-1, MMP-3, and MMP-9 SNP genotype and MMP activity using independent samples t test and analysis of variance." (PMID 17922906, 2007). "Extracellular MMP inducer expression was compared with clinicopathological parameters of tumours, including levels of ki-67, MMP-2, MMP-9 and vascular endothelial growth factor (VEGF), MVD as well as survival time of carcinoma patients." (PMID 17088917, 2006). "Here we report changes in tumor phenotype when FaDu HNSCCs cells are cocultured with WT, MMP-2 null, MMP-9 null or MT1-MMP null fibroblasts in vitro and in vivo." (PMID 16515711, 2006). "Our data suggest a role for MMP-2 during in vitro invasion and MMP-9 and MMP-2 during in vivo tumor cell growth." (PMID 16515711, 2006). "In HT1080 tumor cells, both protein and mRNA levels of TIMP1, TIMP2, MMP2 and MMP9 are increased by butyrate treatment." (PMID 16972989, 2006). "The invasive potential of HNSCC tumor cells were assessed in vitro atop type I collagen gels in coculture with wild-type (WT), MMP-2 null, MMP-9 null or MT1-MMP null fibroblasts." (PMID 16515711, 2006). "In vitro experiments demonstrate that EGF stimulation of EGFR-positive NSCLC cell lines can result in the upregulation of MMP-9 and, likewise, inhibition of EGFR in vivo reduces tumour cell MMP-9 expression." (PMID 15365565, 2004). "This study demonstrates the consistent expression of active and latent forms of MMP-9 and particularly MMP-2 in MM tumour samples by gelatin zymography." (PMID 12771921, 2003). "MMP-9, a target of active MMP-2, was present in the metastatic cell line but expression was down-regulated in the tumour cells in vivo, gelatin analysis revealed that MMP-9 was almost entirely attributable to the murine host, confirmed by PCR." (PMID 11401321, 2001). "Expression of active MMP-2 and MMP-9 and the total MMP activity were greater in tumour compared to normal samples in both tissues (P< 0.05)." (PMID 10496354, 1999). "Consistent with these known mechanisms, we observed that B1451 inhibits tumor cell migration and invasion, which may be mediated by the downregulation of AKT phosphorylation and MMP9 expression." (PMID 41601637, 2026). "In addition, some genes including ABCG1, KRAS, MMP2, MMP9 were inhibited by cyAV3.3 in homospheroids, which indicates the direct effect of ITGA5 inhibition on resistance in tumor cells." (PMID 41584360, 2026). "Instead, Snail's tumor-promoting activity is largely mediated through its cooperation with EGR1/SP1 transcription factors on non-canonical TCACA promoter elements, which upregulate genes such as ZEB1, MMP9, and LEF1." (PMID 42152116, 2026). "Additionally, DIC modulates key tumor microenvironment factors, including VEGF-A, MMP-9, IL-11, and CXCL-12." (PMID 41827705, 2026). "Among these, MMP-2 and MMP-9 are the most extensively studied MMPs, as they facilitate tumor invasion and metastasis by degrading the ECM and basement membrane, thereby creating physical pathways for tumor dissemination." (PMID 41362727, 2026).
tumor (continued). "The current study is a continuation of our previous research, which focused on the role of other proteases such as metalloproteinases (MMP-9 and MMP-2) and their tissue inhibitors (TIMP-1 and TIMP-2) as candidates for tumor markers in gastro-intestinal malignancies, including CRC." (PMID 40725774, 2025). "Similarly, the observed decreases in MMP9 and SDF-1α levels suggest a suppression of extracellular matrix degradation and chemotactic signaling, which are key processes in tumor invasion and metastasis." (PMID 40821654, 2025). "The concomitant elevation of MMP9 and TGF-β aligns with their known roles in extracellular matrix degradation, angiogenesis, and metastasis, as well as immunosuppressive signaling within the tumor microenvironment." (PMID 41304988, 2025). "Finally, neutrophils in the TME secrete vascular endothelial growth factor A (VEGFA) and matrix metalloproteinase 9 (MMP9), promoting tumor growth by supporting angiogenesis and invasion." (PMID 40004489, 2025). "In addition, the expression of metastasis-related markers matrix metallopeptidase 2 (MMP2), MMP9, and intercellular cell adhesion molecule-1 (ICAM1) was decreased, suggesting that METTL3 overexpression suppressed transcription of key tumor metastasis genes." (PMID 41208889, 2025). "This analysis includes the tumor microenvironment, encompassing the infiltration of immune cells such as CD4+ and CD8+ lymphocytes, macrophage polarization, and increases in certain metalloproteinases (MMP-2 and MMP-9)." (PMID 41516122, 2025). "This indicates that IL-6 may promote the expression of PCNA, MMP-9, VEGF, and others following RFA treatment, thereby enhancing proliferation, invasion, and angiogenesis, highlighting its central role in tumor progression." (PMID 41403696, 2025). "Analysis of 161 PDAC cases from the Clinical Proteomic Tumor Analysis Consortium (CPTAC) database revealed that NAT10 mRNA expression was positively correlated with CDC42, matrix metalloproteinase-9 (MMP9), and Paxillin (PXN), which are expressed upon the focal adhesion pathway activation." (PMID 40119353, 2025). "Moreover, matrix metalloproteinases (MMP2, MMP9)—key mediators of ECM remodeling and metastasis—were significantly elevated, reinforcing the model’s relevance for studying EMT-driven tumor progression." (PMID 41149589, 2025). "Furthermore, STAM2 significantly influences the expression of MMP2/MMP9, as well as the phosphorylation of JAK2/STAT3 in cancer cells, thereby enhancing tumor malignancy." (PMID 40149859, 2025). "The authors further demonstrated that the inhibition of the proliferation and invasion of SUM149 and SUM190 breast cancer cells by RhoC knockdown was via the increase of KAI1 (a tumor metastasis suppressor) and decrease of CXCR4 (a tumor progression promoter) and MMP9." (PMID 40214422, 2025). "In TNBC, the interactions between molecules or co-regulatory networks, such as NF-κB may simultaneously participate in the regulation of MMP9 and TNFα, while JAK2 may form cross-pathways with PI3K/Akt, jointly affecting tumor progression." (PMID 40356970, 2025). "HSP90 is secreted by tumor cells, interacting with MMP-2 and MMP-9." (PMID 41369386, 2025). "On the other hand, MMP9 was detected in approximately 55% of the tumors analyzed in the GNL screening, exhibiting strong, widespread expression in the cytoplasm and plasma membrane of cancer cells with a diffuse tumor pattern." (PMID 41041068, 2025). "Neutrophils, particularly those polarized toward the N2 phenotype, are key contributors to tumor angiogenesis through the secretion of multiple pro-angiogenic factors, including FGF2, VEGF-A, ANGPT1, CXCL8, HGF, and MMP9, which collectively facilitate tumor vascularization and metastatic spread." (PMID 40564191, 2025). "However, several studies show that MMP-9 and MMP-12 not only have pro-tumor activity, but they also have anti-tumor activity due to their ability to inhibit angiogenesis in vivo." (PMID 40176865, 2025).
tumor (continued). "Additionally, considering the critical role of matrix metalloproteinases (MMPs) in tumor metastasis, we further examined the effect of SAMD4B on the expression of MMP-2 and MMP-9." (PMID 41154652, 2025). "Moreover, MMP-9 plays a major role in the disruption of the blood–brain barrier (BBB), significantly contributing to the tumor’s aggressive and invasive behavior." (PMID 41154699, 2025). "When co-cultured with THP-1 macrophages, OCSLCs increase the expression of M2 markers such as CD163, while boosting the secretion of anti-inflammatory cytokines like IL-10 and pro-tumor factors such as VEGF and MMP-9, which are characteristic of M2 macrophages." (PMID 40330466, 2025). "In vitro studies showed that the inclusion of MMP-9 did not alter virus infectivity but led to improved tumor regression." (PMID 40061139, 2025). "Also, alternatively activated macrophage (M2) polarization exerts anti-inflammatory and pro-angiogenic property by secreting matrix metalloproteinases (MMP2, MMP9) and growth factors (VEGF, PDGF) which promote tumor growth, metastasis, and invasion." (PMID 40050933, 2025). "Thus, NORAD knockdown in HNSCC-derived tumor stem cells attenuates migration and invasion, lowers the expression levels of EMT-related markers, like MMP2, MMP9, N-cadherin, and vimentin, and upregulates E-cadherin expression." (PMID 41020820, 2025). "Moreover, MMP9, together with MMP2 mediates tumor cells’ invasion through degradation of collagen IV." (PMID 41383620, 2025). "N2 neutrophils exhibit pro-tumor activity, primarily through the secretion of arginase, matrix metalloproteinase-9 (MMP-9), vascular endothelial growth factor (VEGF), and various chemokines, which facilitate tumor metastasis and angiogenesis within the tumor microenvironment." (PMID 40948800, 2025). "In addition, EGCG inhibits tumor cell proliferation and invasion by modulating the ERK MAPK/Akt/PI-3K/NF-kB/AP-1 axis and subsequently suppressing MMP-9 synthesis and activity." (PMID 40565017, 2025). "In the mouse model, the FMT from M group significantly increased Fusobacterium abundance and reduced fecal acetate/butyrate, concomitantly accelerating tumor progression with elevated hepatic and cecal tumor weights and upregulated EMT markers (N-cadherin and MMP9)." (PMID 41472816, 2025). "In addition, the expression of pro-tumor indicators in macrophages (VEGF, MMP9, TGF-β, and HIF-1α) was also higher in S100a4-OE MH-S." (PMID 40658605, 2025). "This elevated CCL5 induces MMP9 and VEGF-A, promoting tumor invasion and angiogenesis." (PMID 41445742, 2025). "Additionally, apigenin inhibits metastasis by down-regulating proteins involved in EMT and tumor cell invasion, such as Snail1, MMP-2, and MMP-9." (PMID 40490812, 2025). "The observed reduction in MMP-7 and MMP-9 mRNA levels suggests that Ht2 may modulate the ECM remodeling, potentially impairing tumor cell invasion and metastasis." (PMID 40282199, 2025). "Similarly, MMP-2 and MMP-9 remodel the ECM, further supporting tumour cell proliferation and metastasis." (PMID 41451221, 2025). "Furthermore, TAMs secrete matrix metalloproteinase-9 (MMP-9), which induces epithelial-mesenchymal transition (EMT) via the transcription factor Snail, enhancing tumor invasiveness." (PMID 40191203, 2025). "Furthermore, Tropomyosin-1 (TPM1) has been found to upregulate E-cadherin expression while downregulating MMP-9 and VEGF expression, collectively inhibiting tumor metastasis in RCC." (PMID 41181710, 2025). "In terms of anti-tumour progression, the active ingredients of XCHT (e.g. Chaihu saponin, baicalein) block HCC cell invasion and metastasis by inhibiting MMP-9 expression and VEGF-mediated angiogenesis, and its combination with sorafenib synergistically reduces tumour cell viability." (PMID 40495147, 2025).